CH25H (cholesterol 25-hydroxylase)
Diseases named in the same sentence as CH25H in open-access papers (continued):
Sharing a sentence is not in itself a finding about the gene and the disease.
tumor (continued). "Under these conditions, knockout of CH25H in DCs led to a notable attenuation of the long-term anti-tumor immunity as seen from inadequate protection elicited by vaccine against tumor growth and death in Ch25hΔDC mice." (PMID 36333297, 2022). "Although CH25H is up-regulated in immune cells that are exposed to inflammatory mediators, the expression levels of CH25H in tumor-infiltrating macrophages and T cells were much lower in comparison to the level in MC38 cells." (PMID 35094065, 2022). "We pre-treated the WT DCs with PGE2, VEGF or LLC tumor cell-conditioned media to downregulate CH25H." (PMID 36333297, 2022). "In all, these results suggest that factors present in the tumor microenvironment downregulate CH25H expression in intratumoral DCs." (PMID 36333297, 2022). "Collectively, these results show that CH25H expression in DCs is required to mediate effective anti-tumor immunity generated by ICD inducing agents." (PMID 36333297, 2022). "A decrease of CH25H in DCs stimulates lysosomal activity and suppresses antigen cross presentation leading to attenuated anti-tumor immunity and accelerated growth of lung tumors." (PMID 36333297, 2022). "In a separate set of experiments, we aimed to examine the epistatic relationship between expression of ATF3 and CH25H in DCs and importance of this relationship for tumor growth." (PMID 36333297, 2022). "Mechanistically, downregulation of CH25H stimulates membrane fusion between endo-phagosomes and lysosomes, accelerates lysosomal degradation and restricts cross-presentation of tumor antigens in the intratumoral DCs." (PMID 36333297, 2022). "In all, these results suggest that ATF3-driven downregulation of CH25H in DCs plays an important function in evading anti-tumor immunity and in stimulation of tumor growth." (PMID 36333297, 2022). "An interrogation of some publicly available datasets reveals that the enzymes Ch25h and Cyp27a1 are expressed in a range of cells within tumours." (PMID 32998240, 2020). "Tumor derived extracellular vesicles downregulate type I interferon receptor and cholesterol 25-hydroxylase (CH25H)." (PMID 32516941, 2020). "CELF5 was low-expressed in tumor cell line; AMACR, CYP27A1, CYP46A1, and CH25H were high-expressed in tumor cell line in CCLE." (PMID 32117422, 2019). "Collectively, these findings indicate that myeloid‐specific knockdown of CH25H blunts tumor growth; however, the reintroduction of 25HC or the administration of the STING inhibitor C176 can reverse this effect, thereby accelerating tumorigenesis and progression." (PMID 41020041, 2025). "Furthermore, CH25H expression was also found to be upregulated in the MDSCs treated with MC38 tumor‐conditioned medium (TCM)." (PMID 41020041, 2025). "Notably, we observed a significantly elevated expression of CH25H in tumor‐infiltrating MDSCs compared to those derived from BM or spleen sources." (PMID 41020041, 2025). "CH25H is prominently expressed in various immune cells, including T‐lymphocytes, macrophages, and dendritic cells (DCs), under physiological conditions, where it plays distinct roles in tumor immunity." (PMID 41020041, 2025). "However, downregulation of CH25H by tumor conditioned media correlates with increased trogocytosis and diminished T cell killing capacity." (PMID 41181711, 2025). "Mechanistically, our results showed that in LUAD, CH25H may be a regulatory factor affecting the immune cell infiltration level, and the resultant tumor development." (PMID 36564433, 2022). "However, no significant decrease in the CH25H expression was observed in LUSC patients with tumor metastasis (P > 0.05), indicating that the CH25H expression level is a potential biomarker for LC metastasis prediction, especially in LUAD." (PMID 36564433, 2022). "However, MSA-2 treatment acted to partially prevent downregulation of Ch25h mRNA levels in response to LLC tumor cell conditioned media." (PMID 36333297, 2022).
tumor (continued). "In addition to the robust induction of type I and type III interferons, expression of APOA1, APOL1, APOL3, and CH25H was increased from 10 to >50-fold, depending on the cell line (C1 or C2) from which the tumor originated." (PMID 34983824, 2022). "Additionally, a study has revealed that LINC01915, a type of long non-coding RNA, inhibited the uptake of TEVs by normal fibroblasts (NFs), cancer-associated fibroblasts (CAFs) activation, and tumor angiogenesis through the miR-92a-3p/KLF4/CH25H axis, thereby impeding tumor growth." (PMID 37720208, 2023). "Whereas DC numbers and CD86 expression were comparable in tumors from these animals, the frequencies of active IFN-γ-expressing CD8+ T cells in the tumor (but not splenic) tissues were increased by ablation of ATF3 but decreased in response to the loss of CH25H in DCs regardless of the ATF3 status." (PMID 36333297, 2022). "Ch25h is also expressed in inflamed peripheral endothelium, and EBI2 mediates B cell recruitment in a tumor model." (PMID 39708807, 2025). "ATF3 suppresses expression of the enzyme cholesterol 25-hydroxylase (CH25H), which in turn promotes trogocytosis between CTLs and tumor cells, leading to T-cell dysfunction and tumor progression." (PMID 41019052, 2025). "The reduction in CH25H expression is regulated by activating transcription factor-3 (ATF3), which is activated by numerous factors in the tumor microenvironment, such as hypoxia and nutrient deprivation." (PMID 39741180, 2025). "Tumor factors can also activate the transcription factor Activating Transcription Factor 3 (ATF3), which suppresses the expression of cholesterol 25-hydroxylase (CH25H), thereby disrupting antigen processing and weakening cross-presentation." (PMID 41050070, 2025). "25-hydroxycholesterol (25-HC) is an oxysterol catalyzed by cholesterol 25 hydroxylase (CH25H), which plays an important role not only in lipid metabolism, immunomodulation and antiviral activity, but also in tumor progression." (PMID 38649856, 2024). "Furthermore, WB analysis revealed higher expression levels of CH25H, Beclin 1, LC3II/LC3I proteins, and lower expression levels of p‐AKT, PI3K, p62 proteins in the tumor+oe‐CH25H compared with the tumor+oe‐NC." (PMID 39428922, 2024). "Among these genes, FCER1A and CH25H have previously been reported to be overexpressed in anti-inflammatory M2 macrophages, and FCER1A+ TAMs have been reported to promote tumor progression by engaging in a positive feedback loop with tumor-initiating cells." (PMID 38722600, 2024). "Accordingly, mice lacking CH25H in DCs exhibit an accelerated tumor growth, decreased infiltration and impaired activation of intratumoral CD8+ T cells." (PMID 36333297, 2022). "Conversely, we demonstrate that tumor microenvironment-associated factors activate ATF3 and downregulate CH25H and its product 25HC thereby alleviating the negative regulation of the lysosomal activity." (PMID 36333297, 2022). "Here we report that this suppression is induced by tumor microenvironment-derived factors, which activate the activating transcription factor-3 (ATF3) transcription factor and downregulate cholesterol 25-hydroxylase (CH25H)." (PMID 36333297, 2022). "Although the supernatant from wild-type MC38 cells promoted the cell growth of MC38 cells in vitro, this effect was not seen for those from MC38-SULT and MC38-ΔCH25H lacking the expression of CH25H, suggesting the relevance of 25-HC to tumor growth." (PMID 35094065, 2022). "Current evidence points towards the importance of tumor-initiating receptor-ligand interactions, e.g., FcγR-antibody complexes, TCR-MHC engagement, CD47-SIRPα signalling, cell intrinsic regulators such as CH25H mediated cholesterol metabolism and ATF3 transcriptional control within the TME." (PMID 41181711, 2025). "However, mice lacking CH25H exhibited poor survival following primary tumor resection and developed more severe metastatic lesions compared to WT mice." (PMID 38405101, 2024).
tumor (continued). "To directly evaluate the importance of CH25H expression in DCs for the anti-tumor immune response we compared the ability of WT and Ch25hΔDC mice to detect antigens generated during the process of the immunogenic cell death (ICD) and develop long term protection against tumor challenge." (PMID 36333297, 2022).
cancer (12 papers, 2015 to 2026). A tumor composed of atypical neoplastic, often pleomorphic cells that invade other tissues. "CellChat analysis revealed that the exhaustion phenotype of CD4+ (Treg, CH25H+, and CCR7+ naive) and active CD8+ (TEM and MAIT) cells was associated with significant intercellular communication with the cancer‐pre cells we identified." (PMID 40860436, 2025). "In our study, M2 macrophages were characterized by the presence of anti-inflammatory markers Gas6, Ch25h, and Olfml3, as well as the pro-cancer marker Hpgds." (PMID 41361104, 2025). "Analysis of CH25H expression in the TCGA‐HNSC dataset revealed significant lower expression of CH25H in cancer samples compared with normal samples." (PMID 39428922, 2024). "Tg6F treatment in the cancer model inhibited the expression of CH25H as measured by IHC in jejunum, and decreased the product of CH25H activity (25-OHC) in jejunum." (PMID 29899427, 2018). "Further knockdown or overexpression experiments of CH25H gene would serve for elucidating the implication of this gene for the therapeutic targets of cancer chemotherapy." (PMID 26577244, 2015). "In the top 20 upregulated DEGs of lymph node‐derived exhausted CD8+ T cells, CXCL13, CXCR4, CH25H, HSPD1, HSP90AA1, and ATF3 have been confirmed to promote lymph node metastasis in several cancer types." (PMID 35184420, 2022).
neurodegenerative disease (4 papers, 2016 to 2025). A disorder of the central nervous system characterized by gradual and progressive loss of neural tissue and neurologic function. "In the CNS, Ch25h is predominantly expressed by microglia, is upregulated under inflammatory conditions, and is part of the gene set expressed by disease-associated microglia (DAM) that remain chronically upregulated in various neurodegenerative diseases." (PMID 40137979, 2025). "Modulation of the levels of CH25H, CYP7B1 and HSD3B7 enzymes directly in the brain may thus be another way to limit the increased chemotaxis or entry of EBI2-expressing encephalitogenic immune cells into the CNS during acute inflammation, neuroinflammatory disease or neurodegenerative diseases." (PMID 39999050, 2025).
bacterial infection (2 papers, 2022 to 2024). "CH25H plays a role in the immune response of salmon to bacterial infections (e.g., Renibacterium salmoninarum and Piscirickettsia salmonis)." (PMID 39211041, 2024). "A mechanism was proposed whereby bacterial infection, or LPS treatment, of macrophages leads to upregulation of IFN expression and CH25H-mediated 25-HC formation." (PMID 34953867, 2022).
neurological diseases (1 paper, 2019). "Among these genes, Ch25h, Trpa1, Cdkn1a, Ly6g6e, Six3, and Opalin are potentially associated with neurological diseases; Lcn2, Serpina3f, Lao1, Trim29, bcl3, and Gkn3 are associated with inflammatory response." (PMID 30804943, 2019).
CH25H also shares sentences with these, for which no sentence is quoted: acute myocardial infarction (1 paper); albuminuria (1); angioedema (1); cardiovascular disease (1); Cerebral ischemia (1); Chronic colitis (1); chronic spontaneous urticaria (1); colon cancer (1); dengue (1); Ebola (1); Glomerulopathy (1); hepatoma (1); HIV-1 infection (1); Insulin resistance (1); Krabbe disease (1); laryngeal squamous cell carcinoma (1); lung (1); lung squamous cell carcinoma (1); metabolic disorders (1); Myelodysplasia (1); myelodysplastic syndrome (1); myeloid neoplasm (1); non-small cell lung carcinoma (1); prostate carcinoma (1); psoriasis (1); rheumatoid arthritis (1); sarcopenia (1); serous adenocarcinoma (1); steatosis (1).